CRACD (capping protein inhibiting regulator of actin dynamics)
Description:
Involved in epithelial cell integrity by acting on the maintenance of the actin cytoskeleton. Positively regulates the actin polymerization, by inhibiting the interaction of actin-capping proteins with actin.
Synonyms: CRAD; KIAA1211
Tractability: No criterion of Open Targets' tractability assessment is met for any kind of drug.
Gene: Protein-coding gene on chromosome 4 (56,049,098 to 56,330,609, forward strand). Ensembl gene ENSG00000109265.
Subcellular location: Cytoplasm, cytosol
Subcellular location (Human Protein Atlas): Nucleoplasm; Golgi apparatus
Gene Ontology:
Molecular function: protein binding
Biological process: negative regulation of barbed-end actin filament capping; positive regulation of actin filament polymerization; epithelial structure maintenance; maintenance of gastrointestinal epithelium
Cellular component: cytosol
Genetic constraint (gnomAD): Loss-of-function variants: 55 observed, 96.67 expected, observed/expected ratio (o/e) 0.57, 90% interval 0.46 to 0.71. The upper end of that interval is the gene's LOEUF score, 0.71, which puts it in group 2 of 6, group 1 being the genes least tolerant of losing a copy. Missense variants: 1,709 observed, 1,629.7 expected, observed/expected ratio (o/e) 1.05, 90% interval 1.01 to 1.09. Synonymous variants: 744 observed, 670.19 expected, observed/expected ratio (o/e) 1.11, 90% interval 1.04 to 1.18.
Homologues: Orthologues: chimpanzee CRACD (99% identical), macaque CRACD (93% identical), mouse Cracd (69% identical), dog CRACD (68% identical), rat Cracd (66% identical), pig CRACD (64% identical), rabbit CRACD (59% identical), tropical clawed frog cracd (41% identical), zebrafish cracd (36% identical).
Diseases named in the same sentence as CRACD in open-access papers:
CRACD is named in the same sentence as 18 diseases in open-access papers, as found by Europe PMC text mining. Sharing a sentence is not in itself a finding about the gene and the disease. The quoted sentences say what the papers report.
glioma (1 paper, 2024). A benign or malignant brain and spinal cord tumor that arises from glial cells (astrocytes, oligodendrocytes, ependymal cells). "CRACD mRNA expression inversely correlated with IFT57 mRNA and with survival in low-grade gliomas, lung adenocarcinomas, and papillary thyroid carcinomas, suggesting that IFT57 rather than CD47 regulates survival in these cancers." (PMID 39201643, 2024).
thyroid carcinoma (1 paper, 2024). "Transcriptome analysis following knockdown of CD47 or IFT57 in thyroid carcinoma cells identified the cytoskeletal regulator CRACD as a specific target of IFT57." (PMID 39201643, 2024).
tumor (9 papers, 2013 to 2025). "In summary, our study provides new insights into the mechanisms of SCLC tumorigenesis by uncovering the unexpected role of CRACD, an actin regulator, in limiting cell plasticity and inhibiting tumor immune evasion." (PMID 41353272, 2025). "Consistent with the inhibition of CRACD mRNA by IFT57 in cells, IFT57 and CRACD mRNA had inverse correlations with survival in each of these tumor types." (PMID 39201643, 2024). "CRACD is frequently inactivated in SCLC21, which led us to hypothesize that CRACD is a tumor suppressor of SCLC." (PMID 41353272, 2025).
CRACD also shares sentences with these, for which no sentence is quoted: breast carcinoma (5 papers); cancer (4); colorectal cancer (4); infection (2); non-small cell lung carcinoma (2); small cell lung carcinoma (2); colon cancer (1); endothelial dysfunction (1); leukemia (1); lung adenocarcinoma (1); lung carcinoma (1); mental disorder (1); myopia (1); papillary thyroid carcinomas (1); stomach cancer (1).